TLR2 (toll like receptor 2)
Diseases named in the same sentence as TLR2 in open-access papers (continued):
Sharing a sentence is not in itself a finding about the gene and the disease.
liver fibrosis (continued). "This study demonstrated that AHCC inhibited HSCs activation by inducing cytoglobin through the TLR2-SAPK/JNK pathway and suppressing collagen production via the TLR4-NF-κβ pathway, resulting in the prevention of liver fibrosis progression." (PMID 39316687, 2024). "Liver fibrosis was confirmed by trichrome staining and was accompanied by a significant increase in proinflammatory IL-6, TNF-α, TLR-2, and TLR-4 and a decrease in anti-inflammatory IL-10." (PMID 39000518, 2024). "A question to ponder is that TLR2 and TLR4 appear to be a synergistic promoter of C. sinensis-induced liver fibrosis." (PMID 36693049, 2023). "TLR2 signaling induced by SEA stimulation promotes M2 polarization in macrophages, which is beneficial for developing liver fibrosis." (PMID 36389166, 2022). "miR-29a overexpression obstructed signaling of toll-like receptor 2(TLR2) and TLR4, key mediators of hepatic fibrosis in Kupffer cells and HSCs, in liver tissues of cholestatic mice." (PMID 33171811, 2020). "Toll-like receptors, especially TLR2 and TLR4, are central mediators of the inflammation during liver fibrosis." (PMID 25954568, 2015). "Toll-like receptor 2 (TLR2) participates in the activation of liver immune cells, stellate cells, and the PI3K/AKT signaling pathway and performs a particular function in regulating inflammation and liver fibrosis." (PMID 40243656, 2025). "Lack of TLR2 in mice inhibits HSC activation, reduces p-JNK and p-p38, and attenuates liver fibrosis induced by CCl4, and SAA1 deficiency substantially reduces p-P38 and p-JNK in the myocardium." (PMID 39105051, 2024). "However, a recent study revealed thatC. sinensis ESPs promoted the production of IL-6 in mouse BECs through the TLR2-mediated AKT and p38 pathways, resulting in the aggravation of hepatic fibrosis in mice." (PMID 39314046, 2024). "TLRs including TLR2, TLR3, TLR4 and TLR9 are expressed on hepatocytes, Kupffer cells, fibroblasts, neutrophils, dendritic cells and endothelial cells in the liver and activated in hepatic fibrosis liver tissue." (PMID 37122694, 2023). "In fact, increased NF-κB levels were found in liver biopsies of HBeAg-negative patients compared to HBeAg-positive patients, and HBeAg-activation of macrophages via the TLR-2/NF-κB signal pathways, where HBeAg binds to the TLR2, has been found in patients with exacerbated hepatic fibrosis." (PMID 37112837, 2023). "Combined with the GO, KEGG and Western blot results, COL1A2, ITGAV, TLR2, ACE, and PDGFRB may be potential targets for PE treatment of liver fibrosis." (PMID 36313326, 2022). "In vitro experiments demonstrated that quercetin treatment led to decreased expression of TGF-β1, α-SMA, HMGB1, TLR2/TLR4, and NF-κB p65 proteins in COL1α1 mRNA, suggesting that quercetin may inhibit HSCs activation and improve liver fibrosis by modulating the HMGB1/TLR/NF-κB signaling pathway." (PMID 39185304, 2024). "Results showed TLR4- and IFN-γ-activated MSC alleviated liver fibrosis in infected mice, without a significant increase of mortality, and unpretreated MSC showed no clear improvement; however, TLR2- and IFN-γ-activated MSC displayed aggravated immunopathology." (PMID 32503644, 2020).
lung carcinoma (39 papers, 2010 to 2025). "A lung cancer-derived extracellular-matrix protein versican is reported to cause a TLR2-dependent activation and M2-phenotype polarization in TAM to induce tumor metastasis." (PMID 32788720, 2020). "The TLR2:TLR6 complex has been linked with enhanced lung cancer metastasis." (PMID 36389785, 2022). "Bacillus Calmette-Guérin-cell wall skeleton (BCG-CWS) leads to tumor regression in lung cancer patients by inducing the secretion of IL-12 and IL-18 via the TLR2/4-macrophage (Mφ)/antigen-presenting cell (APC) axis." (PMID 41293166, 2025). "TLR2 enhances lung cancer cell migration and invasion by promoting the expression of CCL2, IL-6, and MMP-2 through the cAMP-AMPK-TAK1 signaling axis." (PMID 41293166, 2025). "By activating TLR2 signaling and secreting inhibitory molecules such as arginase 1 and eSIRT2, it promotes malignant growth of lung cancer." (PMID 40727252, 2025). "It was found that TLR2/MyD88/NF-κB signal pathway activation via the TRAF6-TAK1 signaling axis is expressed in various malignancies including lung cancer." (PMID 40022036, 2025). "Nontypeable Haemophilus influenzae (NTHi) induces lung epithelial cells to secrete IL-17C via TLR2/4 signaling, thereby promoting lung cancer progression." (PMID 41293166, 2025). "In this study, we demonstrated that FFAR2 was negatively involved in lung cancer progression induced by TLR2 and TLR3 through the suppression of the cAMP-AMPK-TAK1 signaling axis for the activation of NF-κB." (PMID 37287005, 2023). "Functionally, treatment with propionate (an agonist of FFAR2) significantly inhibited human lung cancer migration, invasion, and colony formation induced by TLR2 or TLR3 by attenuating the cAMP-AMPK-TAK1 signaling axis for the activation of NF-κB." (PMID 37287005, 2023). "Collectively, these results suggest that FFAR2 signaling functionally antagonizes lung cancer progression induced by TLR2 or TLR3 via the suppression of the AMPK-TAK1 signaling axis for the activation of NF-κB." (PMID 37287005, 2023). "The epigenetic regulation of TLR2 and TLR3 by DNA methylation has been reported to cause transcriptional activation leading to increased disease susceptibility and severity in lung cancer patients." (PMID 37822929, 2023). "Correlation between TLR2 expression and improved clinical outcomes in lung cancer has also been reported previously in a pan-TLR expression analysis and our data support this finding." (PMID 36351380, 2022). "Using human lung cancer samples and genetically engineered mouse models, we show that TLR2 is active early in lung tumorigenesis, where it correlates with improved survival and clinical regression." (PMID 36351380, 2022). "Mechanistically, TLR2 impairs early lung cancer progression via activation of cell intrinsic cell cycle arrest pathways and the proinflammatory senescence-associated secretory phenotype (SASP)." (PMID 36351380, 2022). "Mice treated with Pam2CSK4 exhibited no observable side effects or altered phenotype, further suggesting TLR2 as a possible drug target in early lung cancer." (PMID 36351380, 2022). "This unique and selective TLR2 activation in mast cells restored the anti-tumor potential hence inhibiting lung carcinoma growth." (PMID 36389785, 2022). "We therefore utilized our early lung cancer GEMM as well as our human early NSCLC samples to investigate the role of the TLR2-regulated SASP in this context." (PMID 36351380, 2022). "For example, activation of TLR2 or TLR4 signals on TAMs increases the lung cancer metastasis via TNF-α and IL-6 production." (PMID 32788720, 2020). "Among the TLRs, TLR2 signaling can promote lung cancer cell growth and lead to reinforced invasiveness and metastasis, and TLR4 signaling can mediate metastasis via enhancing tumor cell invasion, proliferation, and survival of prostate cancer cells." (PMID 28076322, 2017).
lung carcinoma (continued). "In conclusion, the current results showed that Rosa synergistically improves the chemotherapeutic potential of cisplatin in lung cancer cells by suppressing the TLR2/MyD88/ TRAF6/NF-κB signal pathway together with the PI3K/AKT/mTOR and Gal-1 which consequently, inhibits proliferation." (PMID 40022036, 2025). "Activation of TLR2 promotes migration, invasion and colony formation in lung cancer." (PMID 40166469, 2025). "This is particularly applicable to lung cancer patients with high TLR2/3 expression." (PMID 41003841, 2025). "In addition, the activation of TLR2, TLR3, and TLR4 was functionally implicated in lung cancer proliferation, migration, and invasion." (PMID 37287005, 2023). "Importantly, we found that FFAR2KO A549 and FFAR2KO H1299 lung cancer cells exhibited the enhancement of cell migration, invasion, and colony formation induced by TLR2 and TLR3, along with increases in the production of CCL2, IL-6, and MMP2 cytokines." (PMID 37287005, 2023). "Functionally, treatment with propionate (an agonist of FFAR2) significantly inhibited human A549 or H1299 lung cancer migration, invasion, and colony formation induced by TLR2 or TLR3 through the attenuation of the cAMP-AMPK-TAK1 signaling axis for the activation of NF-κB." (PMID 37287005, 2023). "Lung cancer cells can stimulate tumor metastasis by triggering macrophages via TLR2 signaling." (PMID 37925462, 2023). "We found that FFAR2 was negatively associated with TLR2 and TLR3 in lung cancer." (PMID 37287005, 2023). "Both TLR1 and TLR2 have good prognoses for lung cancer and higher expression of these proteins may emerge as useful biomarkers in predicting the outcome or progression of lung cancer." (PMID 36389785, 2022). "Understanding this process identifies TLR2 as a therapeutic target for early-stage lung cancer." (PMID 36351380, 2022). "We then studied the role of the TLR2-regulated SASP in human lung cancer." (PMID 36351380, 2022). "Furthermore, TLR2 stimulation induced by a natural polysaccharide in a lung cancer model induces NK cell activation, proliferation, cancer cell-directed cytotoxicity, and the release of IL-2 and IFN-γ." (PMID 36499361, 2022). "Likewise, lung cancer cells activate macrophages via TLR2/6 and 9 to produce TNF-α and IL-6 resulting in a rapid metastatic progress." (PMID 34476575, 2021). "Indeed, in lung cancer-bearing mice, TLR2 stimulation by treatment with the natural polysaccharide SEP induces NK cell activation, proliferation, cancer cell-directed cytotoxicity, and the release of IL-2 and IFN-γ." (PMID 33321934, 2020). "This study demonstrates that lung cancer cell-derived exosomes could educate naïve MSCs into a new kind of pro-inflammatory MSCs (P-MSCs) by activating TLR2/NF-κB signaling through exosomal surface HSP70." (PMID 27090786, 2016). "Also, TLR-2 plays a tumor suppressor role in early-stage lung cancer." (PMID 39124797, 2024). "Second, we showed that Tlr2 may be a potential therapeutic target in early lung cancer." (PMID 36351380, 2022). "Furthermore, TLR2 knockout reduced the metastatic capacity of this syngeneic lung-cancer model." (PMID 36224342, 2022). "Six key immune genes (TLR2, TLR4, CCR7, IL18, TIRAP and FOXP3) showed cell‐type specific expression patterns in the lung cancer microenvironment." (PMID 41319095, 2025). "This figure presents a detailed analysis of immune responses and genomic states across different cell types in lung cancer, focusing on three key genes: CCR7, TLR4 and TLR2." (PMID 41319095, 2025). "The combined treatment of Rosa canina extract and cisplatin significantly inhibited lung cancer cell proliferation by downregulating PARP-1 and the TLR2/MyD88/TRAF6/NF-κB signaling pathway, as well as the PI3K/Akt/mTOR pathway." (PMID 40022036, 2025). "Our analysis identified six key immune regulatory genes (TLR2, TLR4, CCR7, IL18, TIRAP and FOXP3) that show differential expression between lung cancer and normal tissues and demonstrate potential prognostic value." (PMID 41319095, 2025).
lung carcinoma (continued). "Propionate, an agonist of FFAR2, antagonized TLR2- and TLR3-induced lung cancer migration, invasion, and colony formation by inhibiting the AMPK-TAK1 signaling axis for the activation of NF-κB." (PMID 37287005, 2023). "In summary, our study identified negative regulation by propionate, which is an SCFA and recognized by FFAR2, in TLR2- and TLR3-induced lung cancer progression." (PMID 37287005, 2023). "We next explored the molecular mechanism by which FFAR2 signaling inhibited TLR2- and TLR3-induced lung cancer progression." (PMID 37287005, 2023). "Taken together, these results suggest that FFAR2 antagonizes TLR2- and TLR3-induced lung cancer progression." (PMID 37287005, 2023). "We found that propionate inhibited TLR2- and TLR3-induced lung cancer migration, invasion, and colony formation accompanied by the inhibition of the cAMP-AMPK-TAK1 signaling axis for the activation of NF-κB and the production of CCL2, IL-6, and MMP2 cytokines." (PMID 37287005, 2023). "A549 and H1299 lung cancer cells were treated with vehicle, HKLM (an agonist of TLR2), or poly(I:C) (an agonist of TLR3) in the presence or absence of propionate (an agonist of FFAR2), and the cell migration assay was performed." (PMID 37287005, 2023). "The activated TLR2 : TLR6 can induce TNF-alpha secretion by myeloid cells and enhance lung cancer bone metastasis growth." (PMID 36440359, 2022). "In conclusion, we demonstrate that DP2 promotes cell motility and invasiveness of human lung carcinoma cells, which attributes to the upregulated expression of uPA/uPAR and MMP-2 and activation of FAK/integrin signaling axis via TLR2/4-mediated ERK activation." (PMID 28076322, 2017). "We incubated HEK-Blue cells expressing human TLR2, TLR3, TLR4, TLR5, TLR7, TLR8, TLR9, or the intracellular PRR protein NOD2 with 100 μg/ml DRibbles derived from the mycoplasma free lung cancer cell line UbiLT3." (PMID 27490927, 2016). "Notably, silent information regulator 2 (SIRT2) is secreted by macrophages upon TLR2 or TLR4 activation, further promoting the metastatic process of lung cancer." (PMID 40166469, 2025). "Moreover, the extracellular matrix remodeling and EGFR-mediated signaling axes induced by TLR2 and TLR4 create an optimal condition for the progression and metastasis of lung carcinoma." (PMID 37822929, 2023). "Collectively, our results strongly suggest the FFAR2 signal might antagonize TLR2- and TLR3-induced lung cancer progression via suppression of the cAMP-AMPK-TAK1 signaling axis for the activation of NF-κB." (PMID 37287005, 2023). "The clinical TCGA data showed a significant down-regulation of FFAR2, but not FFAR1, FFAR3, and FFAR4, in lung cancer, and a negative correlation with TLR2 and TLR3." (PMID 37287005, 2023). "Here, using human NSCLC samples and genetically engineered mouse models (GEMMs) of lung cancer, we demonstrate that TLR2 coordinates induction of cell-autonomous and non-cell-autonomous tumor suppressor responses that together impair NSCLC progression." (PMID 36351380, 2022). "Like TLR2, TLR3 also has conflicting roles in lung cancer as either pro- or anti-tumor receptors." (PMID 36389785, 2022). "It has been shown TLRs pathway molecules such as IRAK1and TLR2 have important roles in neoplasm diseases and the significant upregulation of IRAK1 and its involvement in the development of solid tumors including lung cancer have been reported." (PMID 33765916, 2021). "In addition, fatty acid receptor 2 (FFAR2) signaling antagonizes TLR2- and TLR3-induced lung cancer progression by inhibiting the process of cyclic adenosine monophosphate (cAMP)-adenylate-activated protein kinase (AMPK)-transforming growth factor β-activated kinase 1 (TAK1)-NF-κB activation." (PMID 40166469, 2025).
lung carcinoma (continued). "Our results suggest that FFAR2 signaling antagonized TLR2- and TLR3-induced lung cancer progression via the suppression of the cAMP-AMPK-TAK1 signaling axis for the activation of NF-κB, and its agonist might be a potential therapeutic agent for the treatment of lung cancer." (PMID 37287005, 2023). "In lung cancer preclinical models, the administration of PAMPs or synthetic TLR2 ligands induced the differentiation of M1 macrophages that release nitric oxide, IFN-γ and pro-inflammatory cytokines, suggesting that TLR2 activation favors antitumor immune reactions." (PMID 38203626, 2023). "Notably, FFAR2KO human lung cancer FFAR2KO A549 and FFAR2KO H1299 cells showed marked increases in cell migration, invasion, and colony formation in response to TLR2 or TLR3 stimulation, accompanied by elevations in NF-κB activation, cAMP levels, and the production of CCL2, IL-6, and MMP2 cytokines." (PMID 37287005, 2023). "The binding of TLR2 to the adapter protein MyD88 recruits TRAF6 which consequently promotes the activation of the NF-κB Thus, the activation of this pathway may enhance carcinogenesis and development of lung cancer in addition to regulating cancer proliferation." (PMID 40022036, 2025). "However, data supporting this involves GEMMs of lung cancer, which do not fully capture the genetic heterogeneity of human disease; therefore, the effect of TLR2 activation in human cancer may not be as robust." (PMID 36351380, 2022). "In contrast, the down-regulation of FFAR2 in lung cancer did not attenuate the cAMP-AMPK-TAK1 signaling axis for the activation of NF-κB, thereby enhancing TLR2- and TLR3-induced lung cancer progression (right)." (PMID 37287005, 2023).